PBX4 (PBX homeobox 4)
Tractability: PROTAC: ubiquitination databases record sites on it.
Gene: Protein-coding gene on chromosome 19 (19,561,707 to 19,618,732, reverse strand). Ensembl gene ENSG00000105717.
Subcellular location: Nucleus
Subcellular location (Human Protein Atlas): Vesicles
Gene Ontology:
Molecular function: protein binding; DNA-binding transcription activator activity, RNA polymerase II-specific; DNA-binding transcription factor activity, RNA polymerase II-specific; RNA polymerase II cis-regulatory region sequence-specific DNA binding; sequence-specific DNA binding; DNA binding; DNA-binding transcription factor activity
Biological process: animal organ morphogenesis; brain development; embryonic organ development; eye development; neuron development; positive regulation of DNA-templated transcription; positive regulation of transcription by RNA polymerase II; regulation of DNA-templated transcription
Cellular component: chromatin; nucleus; XY body
Genetic constraint (gnomAD): Loss-of-function variants: 26 observed, 33.45 expected, observed/expected ratio (o/e) 0.78, 90% interval 0.57 to 1.08. The upper end of that interval is the gene's LOEUF score, 1.08, which puts it in group 4 of 6, group 1 being the genes least tolerant of losing a copy. Missense variants: 448 observed, 474.01 expected, observed/expected ratio (o/e) 0.95, 90% interval 0.87 to 1.02. Synonymous variants: 199 observed, 183.45 expected, observed/expected ratio (o/e) 1.08, 90% interval 0.97 to 1.22.
Homologues: Orthologues: chimpanzee PBX4 (98% identical), macaque PBX4 (95% identical), rat Pbx4 (80% identical), dog PBX4 (80% identical), pig PBX4 (79% identical), mouse Pbx4 (77% identical), zebrafish pbx2 (63% identical), Drosophila melanogaster exd (60% identical), Caenorhabditis elegans ceh-20 (48% identical), Caenorhabditis elegans ceh-60 (20% identical), Drosophila melanogaster hth (18% identical), Caenorhabditis elegans unc-62 (18% identical), and 2 more. Paralogues in human: PBX3 (70% identical), PBX1 (70% identical), PBX2 (68% identical), MEIS2 (22% identical), MEIS3 (21% identical), MEIS1 (20% identical), PKNOX2 (20% identical), MEIS3P2 (19% identical), PKNOX1 (18% identical), TGIF1 (12% identical), TGIF2 (9% identical), TGIF2LX (8% identical), and 1 more.
Diseases named in the same sentence as PBX4 in open-access papers:
PBX4 is named in the same sentence as 26 diseases in open-access papers, as found by Europe PMC text mining. Sharing a sentence is not in itself a finding about the gene and the disease. The quoted sentences say what the papers report.
dyslipidemia (4 papers, 2016 to 2023). "The SNP of rs16996148 in NCAN-CILP2 or NCAN/CILP2/PBX4 was significantly associated with dyslipidemia in the midlands and east of the Chinese Han population." (PMID 32568739, 2020). "The dyslipidemia of PBX4 loci (rs16996148) was associated with cardiovascular disease." (PMID 35740947, 2022). "Some previous studies have established that the 19p13.11 locus linked together the adjoining genes NCAN and PBX4 with dyslipidemia, and these relationships may now be attributed to TM6SF2." (PMID 32568739, 2020). "Besides, pre-B-cell leukemia transcription factor 4 (PBX4/CILP2 locus) and B-cell CLL/lymphoma 3 genes are considered to be the association factors for dyslipidemia." (PMID 37384286, 2023). "Furthermore, a number of genes within the RNO16 differential segment associated with metabolic syndrome components in human studies showed polymorphisms between SHR and BN-Lx (including Lpl, Nrg3, Pbx4, Cilp2, and Stab1)." (PMID 27031336, 2016).
acute lymphoblastic leukemia (2 papers, 2011 to 2022). Leukemia with an acute onset, characterized by the presence of lymphoblasts in the bone marrow and the peripheral blood. "Recent studies have showed that PBX4 was overexpressed in colorectal cancer and Hodgkin lymphoma, but underexpressed in acute lymphoblastic leukemia." (PMID 35740947, 2022). "Abnormal expression of PBX4 occurred in Hodgkin lymphoma patients and acute lymphoblastic leukemia." (PMID 35740947, 2022).
anaemia (1 paper, 2024). "PBX4 preferentially binds to the promoters of a large number of genes including those for other HD‐containing proteins and ribosomal proteins whose mutations are related to anaemia." (PMID 38230761, 2024).
breast carcinoma (1 paper, 2022). "Breast cancer patients with low PBX4 expression implied a poor DSS (GSE3494-GPL97)." (PMID 35740947, 2022).
cervical cancer (1 paper, 2022). A primary or metastatic malignant neoplasm involving the cervix. "We found that PBX4 was highly expressed in the tissues of testis cancer, thyroid cancer, colorectal cancer, urothelial cancer, stomach cancer, pancreatic cancer, cervical cancer, endometrial cancer, and ovarian cancer from TCGA database." (PMID 35740947, 2022). "The protein expression of PBX4 was increased in cervical cancer, colorectal cancer, endometrial cancer, and lung cancer tissues." (PMID 35740947, 2022). "Meanwhile, the mRNA expression of PBX4 was higher in tissues of testis cancer, thyroid cancer, colorectal cancer, urothelial cancer, stomach cancer, pancreatic cancer, cervical cancer, endometrial cancer, and ovarian cancer." (PMID 35740947, 2022).
colorectal cancer (1 paper, 2022). A primary or metastatic malignant neoplasm that affects the colon or rectum. "Recent studies showed that PBX4 was enriched in the biological processes of cell cycle and cell proliferation in colorectal cancer." (PMID 35740947, 2022). "The results revealed that high PBX4 expression indicated a good OS and disease-specific survival (DSS) of colorectal cancer in the GSE17537 cohort." (PMID 35740947, 2022).
diabetes (1 paper, 2016). "These include CCND2, CILP2, PBX4, SH2B3, SLC6A4, TCF7 and KLF14, which have polymorphisms associated with diabetes risk." (PMID 27029739, 2016).
glioblastoma (1 paper, 2022). The most malignant astrocytic tumor (WHO grade IV). "The PBX4 expression of glioblastoma was negatively associated with cytotoxic T-cell levels and implied some interactions with T-cell exclusion." (PMID 35740947, 2022). "Our findings revealed that the high expression of PBX4 in glioblastoma was correlated with a worse outcome for PD1 immunotherapy, while melanoma patients with a high expression of PBX4 could obtain clinical benefits from ICB therapy and prolong survival time." (PMID 35740947, 2022). "Moreover, glioblastoma patients with PBX4 low expression could achieve clinical benefits with ICB therapy (programmed cell death protein-1 (PD-1)) and prolong survival durations." (PMID 35740947, 2022).
hyperlipidemia (1 paper, 2020). "The genotypic and allelic frequencies of 12 SNPs in the NCAN, TM6SF2, CILP2, PBX4, SUGP1 and MAU2 were substantially different between the hyperlipidemia and normal groups." (PMID 32568739, 2020). "In conclusion, this study shows potential interactions among the NCAN, TM6SF2, CILP2, PBX4, SUGP1 and MAU2, environment and serum lipid levels in hyperlipidemia subjects." (PMID 32568739, 2020).
leukemia (1 paper, 2026). A malignant (clonal) hematologic disorder, involving hematopoietic stem cells and characterized by the presence of primitive or atypical myeloid or lymphoid cells in the bone marrow and the blood. "Together, these results suggest that while Pbx1 functions as an early target of MNX1 in preleukemic cells, Pbxip1 and Pbx4 act as secondary (indirect) targets whose altered expression arises with MNX1 leukemia progression." (PMID 41554854, 2026). "This warrants further investigation into the specific contributions of PBXIP1 and PBX4 to MNX1-driven leukemia and their potential as therapeutic targets." (PMID 41554854, 2026). "However, PBXIP1 and PBX4 are less extensively studied in the context of leukemia." (PMID 41554854, 2026). "While PBX1 has been extensively studied in leukemia, little is known about the contributions of PBXIP1 and PBX4 in this context." (PMID 41554854, 2026). "However, the expression of Pbx4 and Pbxip1 was not significantly affected by Sinefungin treatment, possibly due to their later induction during leukemia development." (PMID 41554854, 2026).
lung carcinoma (1 paper, 2022). "High PBX4 expression suggested a good OS and RFS of lung cancer in the GSE31210 cohort." (PMID 35740947, 2022).
melanoma (1 paper, 2022). A malignant, usually aggressive tumor composed of atypical, neoplastic melanocytes. "On the contrary, low PBX4 expression in melanoma was positively correlated with cytotoxic T-cell levels and suggested a poor prognosis." (PMID 35740947, 2022).
ovarian carcinoma (1 paper, 2022). A malignant neoplasm originating from the surface ovarian epithelium. "High PBX4 expression was correlated with the poor OS in blood cancer (GSE16131-GPL97), ovarian cancer (GSE9891), and LAML (GSE12417-GPL97)." (PMID 35740947, 2022).
cancer (3 papers, 2022 to 2025). A tumor composed of atypical neoplastic, often pleomorphic cells that invade other tissues. "With EPIC, MCPCOUNTER, XCELL, and TIDE algorithms, we found that the expression of PBX4 was negatively correlated with cancer associated fibroblasts in TGCT (all p < 0.05)." (PMID 35740947, 2022). "To investigate the effects of mutation features on the occurrence and development of human cancers, we used cBioPortal and COSMIC to explore the pan-cancer PBX4 mutative status." (PMID 35740947, 2022). "Next, we explored the associations between PBX4 expression and pathological stage and tumor grade to understand the PBX4 mechanism of various cancers." (PMID 35740947, 2022). "The significant difference in PBX4 expression could imply distinct underlying functions in different cancer types." (PMID 35740947, 2022). "Furthermore, five types of PBX4 alteration (mutation, structural variant, amplification, deep deletion, and multiple alterations) were generally found in various TCGA cancers, in which ‘Amplification’ was the main type." (PMID 35740947, 2022). "From the PBX4 mutation sites and their corresponding 3D structures, Q355Nfs*25/Pfs*20 was the most frequent mutation site and the ‘missense’ type was the primary type of pan-cancer mutation (49 missenses/58 mutations)." (PMID 35740947, 2022). "In addition, the TGCT results showed that PBX4 expression was significantly associated with cancer associated fibroblasts in all four algorithms, which implies that PBX4 might affect its transformation and activation." (PMID 35740947, 2022). "PBX4 has been implicated as a potential novel onco-promoter in CRC, as evidenced by its overexpression, which increases cancer cell proliferation and upregulates the expression of markers of epithelial-mesenchymal transition (EMT) and angiogenesis." (PMID 40041860, 2025). "In recent years, an increasing number of studies have uncovered that PBX4 dysregulation is closely related to various diseases, especially cancers." (PMID 35740947, 2022). "We used MethSurv to analyze the influence of PBX4 methylation on the survival prognosis of various cancers." (PMID 35740947, 2022). "We revealed that genetic alterations of PBX4 generally occurred in human cancers and significantly shortened the pan-cancer DFS and PFS." (PMID 35740947, 2022). "Next, we used cBioPortal to investigate the influence of PBX4 alterations on the pan-cancer survival prognosis." (PMID 35740947, 2022). "We explored the associations between PBX4 expression and OS and RFS in different cancer types by using the Kaplan–Meier plotter." (PMID 35740947, 2022). "As for RFS, low expression of PBX4 indicated a poor prognosis in five cancer types (BLCA, LIHC, OV, STAD, and THCA) but a good prognosis in UCEC." (PMID 35740947, 2022). "Next, we used TISDB to explore the correlations between PBX4 expression and molecular subtypes and molecular subtypes across TCGA cancers." (PMID 35740947, 2022). "We further found that PBX4 expression was significantly associated with OS and RFS, but there were distinct differences in different cancers." (PMID 35740947, 2022). "In particular, PBX4 was significantly related to both molecular subtypes and immune subtypes in five cancers, namely BRCA, KIRP, LGG, LUSC, STAD, and UCEC." (PMID 35740947, 2022). "Recent studies have revealed that the dysregulation of PBX4 is closely related to multiple diseases, especially cancers." (PMID 35740947, 2022). "Next, we analyzed the drug sensitivity of PBX4 expression in different cancers from the GDSC database." (PMID 35740947, 2022). "Our results reveal the potential roles of PBX4 in the occurrence, development, and treatment of multiple human cancers." (PMID 35740947, 2022). "Our results showed that PBX4 was differentially expressed in 17 types of human cancer and significantly correlated to the pathological stage, tumor grade, and immune and molecular subtypes." (PMID 35740947, 2022).
cancer (continued). "To further investigate potential roles of PBX4 in different cancers, we used CancerSEA to explore the functional heterogeneity of PBX4 at the single-cell resolution." (PMID 35740947, 2022). "To further study the potential pan-cancer functions of PBX4, we used CancerSEA, GSCA, and Metascape to perform function analysis." (PMID 35740947, 2022). "PBX4 methylation was negatively correlated with PBX4 expression in different human cancers." (PMID 35740947, 2022). "We found that there were significant associations between PBX4 expression and molecular subtypes and immune subtypes of different cancers, which might provide a new entry point for understanding the functions of PBX4 in certain cancers." (PMID 35740947, 2022). "Thus, with TCGA, GEO, HPA, and GTEx datasets, we first explored PBX4 expression across various human cancers." (PMID 35740947, 2022). "For the first time, we performed an integrative analysis of the roles of PBX4 across TCGA cancers." (PMID 35740947, 2022). "Recent studies have revealed that PBX4 involved cancer pathogenesis and progression." (PMID 35740947, 2022). "We found that PBX4 in most TCGA cancers might participate in the activity of apoptosis, the cell cycle, DNA damage, hormone AR pathways, and the inhibition of TSC/mTOR, RAS/MAPK, and RTK pathways." (PMID 35740947, 2022). "Altogether, our integrative analysis could help in better understanding the potential roles of PBX4 in different human cancers." (PMID 35740947, 2022). "Additionally, we found that PBX4 was involved in different functional states of multiple cancers from the single-cell resolution perspective." (PMID 35740947, 2022). "Therefore, we performed immune infiltration analysis to study the critical role of PBX4 in the occurrence and progression of cancers." (PMID 35740947, 2022). "Furthermore, PBX4 expression was significantly different in molecular subtypes and immune subtypes of different human cancers." (PMID 35740947, 2022). "Therefore, for the first time, we performed integrative analysis to provide a comprehensive understanding of the roles of PBX4 in different human cancer types." (PMID 35740947, 2022). "In addition, we found that PBX4 had more counts of the predictive score than three standardized biomarkers of cancer immune evasion (TMB, T.Clonality, and B.Clonality) in the 25 ICB subcohorts." (PMID 35740947, 2022). "The MethSurv results revealed that DNA methylation of PBX4 could significantly affect the survival prognosis of various cancers." (PMID 35740947, 2022). "The results showed that PBX4 was abnormally expressed in most human cancer types." (PMID 35740947, 2022). "In conclusion, our study involved integrative pan-cancer analysis of PBX4." (PMID 35740947, 2022). "Thus, we used TIMER 2.0 to analyze the correlation between PBX4 expression and B-cell plasma in various cancers." (PMID 35740947, 2022). "We explored differential expression of PBX4 across TCGA cancers." (PMID 35740947, 2022). "However, the research on PBX4’s potential roles in 33 cancers from the Cancer Genome Atlas (TCGA) is still insufficient." (PMID 35740947, 2022). "Moreover, we investigated PBX4 protein expression in various cancers." (PMID 35740947, 2022). "PBX4 could serve as a biomarker for cancer detection, prognosis, and immunotherapy." (PMID 35740947, 2022). "Furthermore, we performed DNA methylation analysis of PBX4 across TCGA cancers." (PMID 35740947, 2022). "Thus, PBX4 might serve as an immunotherapy target for various cancers." (PMID 35740947, 2022). "Our findings indicated that PBX4 played an oncogenic role in tumor progression in KIRC and could serve as a biomarker for cancer detection, staging, and prognosis." (PMID 35740947, 2022). "Firstly, we performed an integrative analysis to investigate the pan-cancer roles of PBX4 with multiple public databases while lacking actual clinical data." (PMID 35740947, 2022).
cancer (continued). "Furthermore, we explored the distribution of different types of PBX4’s CNV and the correlations between PBX4 expression and CNV in human cancers." (PMID 35740947, 2022).
tumor (3 papers, 2021 to 2022). "Meanwhile, high expression of PBX4 was significantly associated with good OS prognosis and high tumor grade." (PMID 35740947, 2022). "With the TISIDB database, we found that PBX4 expression was associated with a tumor grade of HNSC (p = 3.04 × 10−8), KIRC (p = 8.29 × 10−5), and LGG (p = 0.0275)." (PMID 35740947, 2022). "Meanwhile, as tumor grade improved, the expression of PBX4 significantly increased in HNSC, KIRC, and LGG." (PMID 35740947, 2022). "Moreover, we used TIMER 2.0 to explore the differential expression of PBX4 between tumor tissues and adjacent normal tissues." (PMID 35740947, 2022). "Moreover, PBX4 expression was positively related to the clinical stage and the tumor grade." (PMID 35740947, 2022). "Furthermore, we used TIDE to find that PBX4 obtained higher predictive values (AUC > 0.5) in 13 of the 25 ICB subcohorts and had more counts of the predictive score than three existing biomarkers (tumor mutational burden (TMB), T-cell clonality (T.Clonality), and B-cell clonality (B.Clonality))." (PMID 35740947, 2022). "Among them, PBX1, PBX2, PBX3 and PBX4, which are members of the PBX gene family, may be involved in tumor cell development." (PMID 33535170, 2021).
PBX4 also shares sentences with these, for which no sentence is quoted: B-cell CLL (1 paper); blood cancer (1); endometrial cancer (1); glioma (1); Hodgkins lymphoma (1); minimal change nephrotic syndrome (1); pancreatic cancer (1); sarcopenia (1); stomach cancer (1); testis cancer (1); thyroid cancer (1).